CDH2 (cadherin 2)
Diseases named in the same sentence as CDH2 in open-access papers (continued):
Sharing a sentence is not in itself a finding about the gene and the disease.
tumor (continued). "We carried out in vitro and in vivo experiments to evaluate the effects of miR-194 and its possible direct targets, IGF1R and CDH2, in tumor growth and metastasis of SOSP-9607 and U2-OS cells." (PMID 25096247, 2014). "In most cancers, the expression of CDH2 increases during tumor progression and induces cell migration and invasion as a mesenchymal marker in the epithelial-mesenchymal transition." (PMID 24705471, 2014). "N-cadherin (neuronal-cadherin, cadherin-2) has been shown to confer a more malignant phenotype in some tumor model systems." (PMID 21941546, 2011). "And in case of SRBCT family of tumors CDH2 provides us a distinctive signature for categorizing the various tumor classes." (PMID 17207284, 2007). "CDH2 belongs to the family of cell-cell adhesion molecules and mostly their reduced expression leads to tumor invasiveness." (PMID 17207284, 2007). "Both simple and multiple linear regression analyses indicated that piR-823 and DNMT3B have a positive regulatory effect on stemness markers (OCT4 and NANOG), while DNMT3B mainly governed EMT-related marker (CDH2) expression, further supporting their involvement in tumor progression and metastasis." (PMID 41596471, 2026). "Comparison between the high- and low-CDH2 expression groups revealed that tumors with higher CDH2 expression exhibited a significantly higher proportion of activated natural killer (NK) cells within the tumor immune microenvironment." (PMID 41596365, 2026). "Differential expression analysis of tumor cells, identified using the “FindMarkers” function, revealed that CDH2 was significantly upregulated in the resistant group (expressed in 22.6% of cells), whereas its expression was low or undetectable in the sensitive group (p = 0.00087)." (PMID 41596365, 2026). "Notably, the association between CDH2 and the TLR pathway a central mediator of innate immune responses implies a potential role for CDH2 in regulating tumor–immune interactions." (PMID 41596365, 2026). "Also, we verified that all the patients’ ascites EVs displayed EV-positive markers of CD63 and PDCD6IP (ALIX) proteins and tumour metastasis markers of N-cadherin (CDH2), claudin-1 (CLDN1) and angiogenin (ANG)." (PMID 40993350, 2025). "Taken together, the regulatory role of CDH2 in the tumor immune microenvironment suggests that it could serve as a promising target for anti-tumor immunotherapy." (PMID 40255563, 2025). "Particularly, spatial transcriptomics combined with exosome-tracking approaches enable precise localization of exosome–immune interactions in the tumor microenvironment, which could be applied to validate CDH2-centered redox licensing and EMT–CSC coupling." (PMID 41462674, 2025). "Combined RNAscope and immunofluorescence for CDH2, AXL, FAK, PD-L1, and miR-210, integrated with spatial transcriptomics, could map hybrid E/M niches and EV-linked immune states across tumor stages." (PMID 41462674, 2025). "The results confirmed that CDH2 was significantly overexpressed in tumor tissues." (PMID 40255563, 2025). "We analyzed the expression of the epithelial cell marker gene CDH1 and the mesenchymal cell marker gene CDH2, finding that CDH1 expression decreased while CDH2 expression increased in malignant tumor epithelial cells as the tumor progressed from primary to metastatic stages." (PMID 41050411, 2025). "Patients stratified by combined CDH2^high/miR-210^high expression could be prioritized for RAX-targeted intervention trials, analogous to PD-L1 or tumor mutational burden (TMB)-based enrichment in immunotherapy trials." (PMID 41462674, 2025). "Also, it is most important to demonstrate that the genes SNAIL2 and CDH2 were remarkably overexpressed in the N2 group, which marks the ability of the tumor cells to migrate to several lymph nodes." (PMID 38539520, 2024). "Increased CDH2 expression signifies enhanced invasion and migration ability of tumor cells." (PMID 38397980, 2024).
tumor (continued). "Furthermore, the western blotting results showed that CDH1 expression was not significantly different between the recurrent and primary tumours, whereas increased expression of CDH2 was observed in the recurrent ACP group." (PMID 38594611, 2024). "However, for the ATC01 spheroids, the CDH2 to CDH1 ratio was relatively closer to the ones in the parental tumor in comparison to monolayer cultures." (PMID 38500204, 2024). "In addition, the expression of CDH1 was amplified, while that of CDH2 was attenuated in the tumours dissected from the shIGFBP7 group." (PMID 39351597, 2024). "Co-culture of mouse tumor cells with Eo33, compared to Eo5, induced more substantial up-regulation of the epithelial marker E-Cadherin/Cdh1 and down-modulation of the mesenchymal molecule N-Cadherin/Cdh2." (PMID 39061080, 2024). "Only four tumor types showed a consistent alteration in mRNA levels of N-cadherin (gene: CDH2) across the independent datasets: increased CDH2 levels in thyroid (THCA) and kidney (KIRP), decreased CDH2 mRNA levels in colon (COAD) and prostate (PRAD) adenocarcinoma." (PMID 36880595, 2023). "Results revealed that elevated levels of CDH2 and Ki67 expression were detected in the control group, while down-regulated levels were observed in the miR-187 overexpression group, further supporting the suppressive effect of miR-187 on tumor growth." (PMID 37531206, 2023). "Consequently, the abnormal expression of CDH2 can enhance the migration and invasion ability of tumor cells, promote cell–cell interaction, and play an essential role in tumor progression and metastasis." (PMID 37684273, 2023). "Importantly, Cdh2-KO cells showed significantly reduced invasion and metastasis behavior, and slower tumor growth." (PMID 35890278, 2022). "CDH2/4/11/12 were all associated with EMT signaling in the GSEA and were seen to be important inflammation- and immune-related gene sets and cancer-related gene sets in tumor metastasis." (PMID 36315446, 2022). "However, the positive cells of NCAM1 (2.36%) and CDH2 (31.86%) accounted for a very low proportion of the total tumor cells in these seven S100P- iCCAs." (PMID 35347134, 2022). "The expression of CDH2 was significantly higher in THCA tumor tissues compared to normal tissues." (PMID 35756646, 2022). "Similarly, CDH2 expression in 58 paired tissues exhibited markedly higher in tumor tissues than in normal tissues in THCA." (PMID 35756646, 2022). "Our study demonstrated that an ultrasound combined with GVs could effectively mediate CRISPR/Cas9 gene editing of a Cdh2 gene to inhibit tumor invasion and metastasis." (PMID 35890278, 2022). "The overexpression of CDH2 on tumor cells can mediate invasion and metastasis." (PMID 36552219, 2022). "Since loss of the tumor suppressor DLC1 leads to increased HCC growth, we next investigated whether the newly identified target genes VCAN, TSPAN5 and CDH2 affect tumor characteristics such as proliferation or invasion." (PMID 34771537, 2021). "Moreover, several previous studies demonstrated that expression of CDH2 has a positive correlation with SNAI2 in tumor tissues." (PMID 32788880, 2020). "Moreover, while some data indicate that Cdh2 expression correlates with tumor grade or invasiveness other studies reported opposite results." (PMID 31426573, 2019). "Similar to cadherin-2, this molecule is involved in the formation of adherens junctions and mediates metastasis of tumor cells and synthesis of collagen and elastin, thereby regulating the mechanical properties and contractile function of tissues, as well as cell adhesion and proliferation." (PMID 31546729, 2019). "An alternative explanation could be that Cdh4 expressing tumor cells can form mainly heterophilic interactions with parenchymal cells which expresses only Cdh2." (PMID 31426573, 2019). "Furthermore, the expression of neuronal(N)-cadherin (CDH2), normally expressed from mesenchymal cells, promotes cellular motility and the invasiveness of tumor cells." (PMID 29783778, 2018).
tumor (continued). "In addition, CDH2 plays a significant role in epithelial-mesenchymal transition, a pivotal event for tumor cell acquisition of metastatic ability." (PMID 30414611, 2018). "Using the Cancer Genome Atlas UBC tumor collection, we evaluated whether PTEN loss of function was linked to E-cad (CDH1) downregulation or N-cad (CDH2) expression." (PMID 27863432, 2016). "CDH1 levels decreased while CDH2 levels increased in siIGFBP2/CDDP-treated Flo-1 cells as compared to mock-treated or siNon-targeting controls, indicating an “E-cadherin to N-cadherin switch” that has been previously shown to contribute to tumor cell motility and invasion." (PMID 26317790, 2015). "The EGFR mutated SNAI1 reactivated tumor express TWIST1, VIM and CDH2 (sample 288) suggesting that TWIST1 and SNAI1 might interact to drive full mesenchymal phenotype." (PMID 22272264, 2012). "The repression of CDH2 may therefore be a key element of SAMD1’s tumor-suppressive role in PDAC." (PMID 39137238, 2024). "This shows that CDH2 and its ANGs may affect gene expression, cell cycle, and energy metabolism by regulating histone acetylation, protease activity, and ion channels, ultimately affecting tumor proliferation, differentiation, and metastasis." (PMID 39545598, 2024). "The Cdh2-KO cells were then tested in vivo to see if they might inhibit tumor metastasis." (PMID 35890278, 2022). "Additionally, the expression of TWIST1, SNAI1, FN1, and CDH2 also showed significant association with NUTF2, suggesting that NUTF2 may play a major tumor-promoting role in the Lumina A BRCA subtype." (PMID 35155261, 2022). "PPI analysis indicated that the levels of the mRNAs encoding RBPJ, SKP1, CTNNB1, CDH2, SCG2, VGF, and TFF3 were significantly increased in PanNEN tumor tissues compared with the matched paratumor tissues and may be involved in the DNER signaling pathway in PanNENs." (PMID 33329729, 2020). "Interestingly, 68% of tumor tissues showed co-expression of Golm-1 and CDH2." (PMID 28486946, 2017). "Here, for example, we can see that CEACAM6 has high expression in the smaller noninvasive tumor region at the bottom, while CDH2 (N-cadherin) and DCAF7 have high expression in the larger invasive tumor region at the top." (PMID 41160880, 2026). "CDH1 and CDH2 were canonical epithelial and mesenchymal markers, respectively, commonly used to evaluate EMT status and tumor aggressiveness." (PMID 41596471, 2026). "Immunohistochemistry assays revealed that treatment of 3-MA resulted in a striking decreased expression of CDH2 and SNAI in the NSD2-overexpressing MDA-MB-231 tumor." (PMID 40097917, 2025). "This study reveals that tumor cell‐derived EVs‐LncRNA HOTAIR, that upregulates CDH2 expression by sequestering miR‐375, promotes immune evasion and PTX resistance in EC cells." (PMID 40235720, 2025). "N‐cadherin/CDH2, a key EMT biomarker and effector, was enriched in primary tumor cells that showed upregulation of SNAI2 and diminished expression of E‐cadherin." (PMID 40600748, 2025). "During the metastatic process, the expression of CDH1 decreased while CDH2 increased in malignant tumor epithelial cells, consistent with previous studies that implicate EMT signaling in tumor metastasis." (PMID 41050411, 2025). "A heatmap analysis was conducted using a TCGA dataset of LUAD patients for TNFAIP6, PLK1, and mesenchymal markers including CDH2, SNAI1, and SNAI2 in paired normal tissue (left, normal) and adjacent tumor tissues (right, LUAD) depending on stages." (PMID 40860188, 2025). "When interacting with FOXQ1, these proteins can convert each other into either transcription activators or repressors, thereby inducing or suppressing the expression of N-cadherin (CDH2 gene), a key regulator of tumor invasion and metastasis." (PMID 41347087, 2025). "This is supported by the positive correlation between the expression levels of AR, CDH2, PRKAA1 and tumor purity." (PMID 39342345, 2024).
tumor (continued). "Third, decreased expression of individual tumor-intrinsic mesenchymal markers was confirmed in HER2 positive biopsies; mesenchymal markers such as CDH2, ZEB1, and SNAI1 showed higher expression in the HER2 negative cohort (p < 0.001)." (PMID 39151279, 2024). "CDH2 promotes EMT by reducing cell-cell adhesion and facilitating the detachment of tumor cells from the primary tumor, enabling their migration and invasion into surrounding tissues." (PMID 39342345, 2024). "Through RNA-Seq analysis of HNSCC samples (3 tumors and 3 para-carcinoma tissues), we identified 8 pivotal marker genes (PCDH7, CDH2, ITGA3, SEMA7A, TMEM132A, CD276, TMEM2, GPR158) that were overexpressed in tumor specimens." (PMID 38548747, 2024). "The decrease in the invasion and migration ability of tumor cells is often accompanied by increased expression of the core molecule CDH1, decreased expression of CDH2, and decreased expression of VIM." (PMID 38397980, 2024). "QRT‐PCR assays confirmed that the epithelial gene Cdh1 was significantly downregulated while the mesenchymal genes, Cdh2, Vim and Fn1, were significantly upregulated in the TMPL tumor organoids compared to the TMP organoids." (PMID 39049720, 2024). "Concurrently, the mesenchymal cell marker N-cadherin (CDH2) is upregulated to facilitate cell migration and invasion to promote tumor progression and metastasis." (PMID 38822380, 2024). "The genes CDH1, CDH2, and MMP9, which are involved in promoting tumour cell metastasis, was significantly increased in H128-LM cells and H128-BPM cells compared to H128 cells." (PMID 38644473, 2024). "Tumours derived from GATM-knockdown cells expressed lower levels of Snai1, Cdh2 and Rhoa than tumours-derived from controls." (PMID 37370109, 2023). "miR-124 acts as a tumor suppressor and inhibits cancer cell proliferation by targeting oncogenic CD164 and Cadherin-2 (CDH2) signaling pathways in NSCLC." (PMID 37508353, 2023). "The mesenchymal markers ACTA2, CDH2, CDH11, and VIM are involved in proliferation, generation of stem-cell-like cells, and tumor progression." (PMID 37345150, 2023). "Mesenchymal to epithelial conversion in vivo reinitiates proliferation, potentially mediated by heterotypic adherence junctions between newly re-expressed tumor-cell E-cadherin (CDH1) and osteoblast N-cadherin (CDH2)." (PMID 37296983, 2023). "Together with the altered CSF2, the two cell adhesion proteins, osteoblast-cadherin (CDH11) and N-cadherin (CDH2) were downregulated, suggesting that osteoclasts decrease the tumor cell ability to adhere to mesenchymal cells in the microenvironment." (PMID 35971022, 2022). "We and others have recently demonstrated that CUL4B regulates the expression of several tumor suppressors, including MYCN, PIK3CA, HER2, SOX4, C-MYC and CDH2 at the posttranscriptional level." (PMID 35784474, 2022). "The results showed that increased CDC42, CDH2, ERBB2, JAG1, YAP1, and YWHAZ were found in the tumor tissues." (PMID 35340237, 2022). "Similar to the results of mRNA levels from the TCGA database, the protein expression levels of CDH2 and FRMD3 were significantly higher in tumor tissues of THCA than in normal tissues." (PMID 35756646, 2022). "Xenograft tumor of HCT 116 showed an increased expression of neuronal genes MAP2 and SYN1, neural stemness genes CDH2, MSI1, NCAM1, SOX2/9, VIM and ZEB2, and genes for mesodermal and endodermal tissues (ACP5, AFP, DESMIN, HNF4A and KRT8)." (PMID 33468253, 2021). "Knocking down LINC02535 also significantly inhibited the EMT, a key contributor to tumor invasion and metastasis, by inducing the expression of SNAIL, MMP2, and CDH2 (N-cadherin)." (PMID 33869203, 2021). "CDH1 (E-cadherin) expressions always served as tumor suppressors during carcinoma EMT, while the hallmarks of EMT are the upregulation of CDH2 (N-cadherin) and vimentin." (PMID 34631545, 2021).
tumor (continued). "A positive correlation was also found between EMT markers (FN1 and CDH2) and the IGF‐1R expression in OSCC tumours." (PMID 34528373, 2021). "A positive correlation was also found between Cadherin‐2 (CDH2, also known as N‐cadherin) and IGF‐1R expression in OSCC tumours (p < 0.01)." (PMID 34528373, 2021). "To further confirm the prognostic value of the hub genes with prognostic values, we used immunohistochemical (IHC) staining to detect the protein expression of CDH2 and SPARCL1 in normal tissues and tumor tissues." (PMID 34422629, 2021). "In the univariable Cox analysis, clinical tumor stage, age, and the expression levels of NFE2L2, ITGAV, GET4, FERMT2, CRB3, CDH2, and BCL2L1 were prognostic factors for OS." (PMID 33850477, 2021). "The expression of CDH2, MDM2 and TNFSF10 was significantly upregulated in tumor tissue, while expression of PAX8 and FERMT2 was significantly downregulated." (PMID 33850477, 2021). "Consistently, we found the downregulation of N-cadherin (CDH2) and α-catenin (CTNNA1) genes in the tumor mass of TG-hLH-R-frt-200 mouse, according to what occurs in human ECs35." (PMID 33893331, 2021). "Remarkably, we have also found that the expression of PD-L1, which has an immunosupressive function in the anti-tumor immune reaction, correlated inversely with EMT transcription factors related to barriers (CDH2, CAV2, DSC2, and IL1RN)." (PMID 34527572, 2021). "The expression level of CDH2(r = 0.263, P = 3.54 × 10−7), CDH6 (r = 0.307, P = 2.04 × 10−9) and CDH10 (r = 0.33, P = 9.99 × 10−11) in GC tumor tissues were closely related to CD4 + T cell immune infiltration." (PMID 34880371, 2021). "IHC analysis of subcutaneous tumours generated by SPON2‐knockout SGC‐7901 cells revealed that compared with the controls, the levels of CDH1 expression increased, those of CDH2, VIM and p‐ERK1/2 decreased, and those of ERK1/2 were unchanged." (PMID 31691494, 2020). "We further compared the mRNA expression of CDH1, CDH2, SNAI1, SNAI2, VIM, TWIST1 between ccRCC tumor samples and adjacent normal tissues respectively based on RNA-sequence data from TCGA database." (PMID 31915310, 2020). "CTNNB1 and CDH2 were localized at the cell membrane, and we found strong cell membrane positivity of CTNNB1 and CDH2 in tumor tissue compared with paratumor tissue, with significant differences (P < 0.05)." (PMID 33329729, 2020). "In the next step, expression level of stemness relatedgenes (OCT4, SOX2, KLF4, c-MYC and NANOG) and EMTtranscription factors (CDH1, CDH2, SNAIL1, TWIST1,TWIST2 and ZEB1) were evaluated in all tumor samples andmammospheres." (PMID 31376329, 2020). "Oncomine datasets demonstrated CDH1, CDH2, SNAI1, SNAI2, VIM, TWIST1 in 20 types of cancers between tumor and normal tissues." (PMID 31915310, 2020). "Two of the clusters have high expression of genes related to mesenchymal phenotype (e.g., CDH2, SNAI2, ZEB1, TWIST1, and VIM) which were assigned as tumor cells with EMT characteristics (EMT+)." (PMID 32988401, 2020). "The correlations of ZNF750 with SNAI1, VIM, CDH2 and CDH1 were verified with our RNA sequencing data of 155 paired of ESCC and matched non-tumor tissues." (PMID 32042337, 2020). "The levels of eight hub genes expression (FN1, CCND1, CDH2, CXCL12, MET, IRS1, DCN and FMOD) in PTC and para-cancerous non-tumor tissues were detected by qRT-PCR." (PMID 32714651, 2020). "In AC, miR-9-5p exerts a tumor suppressive role and the EMT phenotype is achieved by low levels of miR-9-5p, which enable the upregulation of CDH2 via TWIST1." (PMID 31888045, 2019). "In contrast, panobinostat-treated TU-BcX-2 K1 tumor explants increased CDH1 and suppressed VIM and CDH2 mRNA expression, potentially indicating trans-differentiation to a more luminal-like phenotype." (PMID 30845999, 2019).